CXCL8 (C-X-C motif chemokine ligand 8)
Diseases named in the same sentence as CXCL8 in open-access papers (continued):
Sharing a sentence is not in itself a finding about the gene and the disease.
tumor (continued). "For instance, IL-8 (CXCL8) promotes tumor angiogenesis by binding to CXCR1 and CXCR2 receptors." (PMID 36246978, 2022). "Together, those results reveal the strong role of CXCL8 to reflect tumor microenvironment." (PMID 36532065, 2022). "Previous review has demonstrated that CXCL8 could be secreted by tumor cells and subsequently promote themselves growth and/or inhibit apoptosis." (PMID 35372515, 2022). "Lurbinectedin has a direct effect on the tumor microenvironment by modifying the immune-regulatory properties of tumor associated macrophages, where it significantly inhibits the transcription of CCL2, CXCL8, and VEGF." (PMID 34739582, 2022). "In addition to its regulatory properties, CXCL8 is a potential biomarker to predict tumor progression and prognosis in many malignancies." (PMID 36072669, 2022). "Analysis of the relationship between serum CXCL-8 concentrations and clinicopathological features indicated that serum levels of CXCL-8 were significantly associated with distant metastasis and tumor size, which was further verified by Spearman's correlation test." (PMID 36567905, 2022). "Furthermore, the estimated score showed higher CXCL8 had a lower purity of tumor cells (p < 0.0001)." (PMID 36532065, 2022). "In summary, our results suggest that serum CXCL-8 may be a better biochemical tumor marker for CRC diagnosis than routine clinical blood-based markers or may be a suitable adjunct." (PMID 36567905, 2022). "In CRC, we found that Anaerolineae and TM7—oral microbes that also inhabit the human gastrointestinal tract, and are known to promote oral and colorectal tumorigenesis—are negatively correlated with host genes enriched in the tumour-promoting interleukin-10 signalling pathway, such CXCL8 and IL1RN." (PMID 35577971, 2022). "Pro-tumor feedback loops mediated by CXCL8 has been observed in multiple types of cancers." (PMID 35372515, 2022). "Previous reviews and many recent studies have illustrated that multiple cell types in TME can directly secret CXCL8, or regulate the expression of CXCL8 in cancer cells, or be regulated by CXCL8 derived from cancer cells to promote tumor invasion and migration." (PMID 35372515, 2022). "Kaplan–Meier survival analysis revealed a significant association between stromal CXCL8 and CD68+ cell density, with a significant reduction in survival of patients whose tumours were high for both compared to those high for one and low for both markers (HR = 1.880, 95% CI: 1.299–2.720, p = 0.001)." (PMID 35879507, 2022). "Signaling pathway analysis suggested that increased CXCL8 and decreased LINC00261 may participate in hypoxia-induced tumor angiogenesis and cause a poor prognosis for the patients." (PMID 36078096, 2022). "CXCL8 is an indispensable important inflammatory response factor and immunosuppressive factor in the tumor microenvironment and has been shown to be up-regulated in a variety of tumor tissues or tumor patient’s serum." (PMID 36358719, 2022). "For example, interleukin (IL) 8 (encoded by CXCL8) is a potent pro‐inflammatory neutrophil and myeloid‐derived suppressor cell (MDSC) chemoattractant with a short circulating half‐life, known to reflect systemic tumour volume." (PMID 35394069, 2022). "Published reports collectively suggest that CXCL8 can recruit tumor-associated macrophages (TAMs), myeloid derived suppressor cells (MDSCs), and neutrophils to the TME, resulting in dampening the anti-tumor immune response of cytotoxic immune cells." (PMID 35372515, 2022). "In conclusion, EBV-upregulated CXCL8 expression promotes VM formation in GC via NF-κB signaling, and CXCL8 might serve as a novel anti-tumor target for EBVaGC." (PMID 35321317, 2022). "We hypothesise that one mechanism of tumour promotion induced by CXCL8 is by its augmentation of the expression of PD‐L1 on tumour cells." (PMID 35879507, 2022).
tumor (continued). "Additionally, patients with CRC with a tumor size ≥5 cm showed significantly higher CXCL-8 and CEA concentrations than those with a tumor size <5 cm (p < 0.05)." (PMID 36567905, 2022). "CXCL8 is upregulated in various cancers and are correlated with tumor stages and patient prognosis." (PMID 35898871, 2022). "Notably, we also found that serum concentrations of CXCL-8 were positively correlated with metastases and tumor size." (PMID 36567905, 2022). "We evaluated the transcriptional level of CXCL8 in 20 tumor types through TCGA database." (PMID 36358719, 2022). "As metabolism reprogramming has already become a hallmark of cancer, the relationship between CXCL8 and tumor metabolism reprogramming is not widely explored." (PMID 35372515, 2022). "Additionally, there are many excellent reviews about other mechanisms of CXCL8 in tumor therapy resistance." (PMID 35372515, 2022). "Patients with high systemic neutrophil counts and high tumour stromal CXCL8 expression observed a mean survival time of 150 (95% CI: 138–161) months, compared with 122 (95% CI: 110–135) months for one high and 88 (95% CI: 59–118) months in patients low for both markers." (PMID 35879507, 2022). "Furthermore, CXCL8 is highly correlated with the tumor microenvironment and immunotherapy response in CRC." (PMID 36532065, 2022). "In addition, activation of GPR68 caused the stimulation and secretion of proinflammatory mediators such as IL‐6 and IL‐8 (CXCL8), which triggered tumor progression." (PMID 35311103, 2022). "The FOXS1/CXCL8 axis promoted tumor cell migration, invasion, angiogenesis, and metastasis in CRC, suggesting that FOXS1/CXCL8 may be a novel target in disrupting tumor-associated angiogenesis and in controlling advanced CRC." (PMID 35898871, 2022). "Notably, CXCL8 binds CXCR1/2 in the tumor microenvironment, promoting tumor cell proliferation and growth through autocrine and paracrine mechanisms." (PMID 36072669, 2022). "CD14CTX had increased expression of several tumor-associated macrophage (TAM)- and/or myeloid-derived suppressor cell (MDSC)-related cytokines, including IL6, TGFB1, and CXCL8." (PMID 36130508, 2022). "In the in vivo assays, we confirmed that CXCL8 promoted the formation of the subcutaneous tumor." (PMID 35562774, 2022). "Similarly, patients with high tumour stromal CXCL8 and high systemic neutrophil counts observed worse outcomes than those high for one or low for both (HR = 2.037, 95% CI: 1.464–2.834, p < 0.001)." (PMID 35879507, 2022). "Furthermore, in triple-negative breast cancer (TNBC), CXCL1, CXCL2, and CXCL8 are all highly expressed, which is beneficial for tumor blood vessel formation." (PMID 36612163, 2022). "Additionally, CXCR1 and CXCR2 chemokine receptors display a high affinity for IL-8 (CXCL8), secreted by tumor cells in different cancer types." (PMID 35990652, 2022). "This upregulation of CXCL8 signal plays important roles in the tumor microenvironment." (PMID 36276076, 2022). "Effects of CXCL8 on tumor cells could also influence the TME or be influenced by the components of TME." (PMID 35372515, 2022). "Dependence on the age of patients, the stage of the disease, the presence of mutations in the EGFR-signaling pathway on the level of CXCL8 in the tumor was not revealed." (PMID 36517518, 2022). "Furthermore, various neutrophil-attracting chemokines (CXCL1, CXCL2, CXCL5, CXCL6, and CXCL8) promote the migration of neutrophils to the tumor site through CXCR1 and CXCR2 receptors." (PMID 36091114, 2022). "CXCL8 is a promising prospective prognostic and tumor TME-related cluster." (PMID 36246607, 2022). "The chemokine CXCL8 has been found to play an important role in tumor progression in recent years." (PMID 35372515, 2022). "CXCL8 enhances angiogenesis and tumor growth through Ras/MAPK/PI3K activation." (PMID 35011369, 2021).
tumor (continued). "In this regard, increased CXCL8 production contributed from increased TAM presence and direct activation of CXCL8 transcription in tumours with USP12 downregulation may greatly contribute to resistant phenotype to PD-1 blockade." (PMID 34381028, 2021). "Also, WCE rich in flavonoids suppressed IL-6, CXCL1, and CXCL8 thus reducing tumor-elicited infiltration MDSCs, TAMs, and endothelial cells accompanied by reduced STAT3 activation, in MDSCs in PC-3 and DU145 prostate cancer xenografts." (PMID 34950252, 2021). "In addition, chemokine receptors CXCR1/2 and their ligand CXCL8 are essential for the activation and trafficking of inflammatory mediators as well as tumor progression and metastasis." (PMID 33802234, 2021). "SB225002-mediated inhibition of CXCL8 prevented tumor supernatant-induced formation of tubules." (PMID 34124076, 2021). "The treatment with CXCL8 siRNA oligos in KTN1-upregulated groups reduced the tumor growth." (PMID 34219129, 2021). "Moreover, physical interactions between TNBCs and hBMMSCs primed with TNFα or IL-1β, activates Notch1, which leads to CXCL8 production and increased tumor cell migration and invasion." (PMID 33849537, 2021). "On the other hand, human tumor studies showed that chemokines such as CXCL1 and CXCL8 are produced by tumor cells, macrophages, and neutrophils to recruit further neutrophils, macrophages, and sometimes myeloid-derived suppressor cells (MDSC) where the MDSC would prevent the killing of tumor cells." (PMID 34437478, 2021). "Interestingly, the analytical results showed high expressions of the MYC/CXCL8/TIMP1 oncogenes in tumor samples compare d to normal samples." (PMID 34440739, 2021). "However, the tumor growth was significantly reduced in mice bearing tumors expressing CXCL8 siRNA oligos groups, compared with the KTN1 overexpression groups (n = 6)." (PMID 34219129, 2021). "For instance, the angiocrine factors CXCL1 and CXCL8 induce tumor cell invasion." (PMID 34073394, 2021). "Moreover, it is known that IL-8/CXCL8 induces epithelial-mesenchymal transition (EMT) in tumor cells via the PI3K/Akt signaling axis." (PMID 34611474, 2021). "High expression of CXCL8 in tumor tissues was correlated with a high infiltration of TAMs." (PMID 34572939, 2021). "For example, the level of CXCL8 was upregulated in endothelial cells co-cultured with HNSCC, showing that CXCL8 might play a pro-oncogenic role in the pathobiology of tumor cells." (PMID 33892811, 2021). "In human gastric carcinoma, CXCL8 levels correlated with tumor vascularization." (PMID 34503058, 2021). "Interestingly the HS prepared from the tumor lobe showed a significantly increased binding affinity to CXCL8 (567 ± 124 nM) compared with the healthy lobe, which is comparable in binding to cHS2." (PMID 34576979, 2021). "However, that study have suggested that the regulation of IL-8 within the tumor and microenvironment play a critical role, but the impact of tissue microenvironment-derived CXCL8 and CXCR2 to date remains difficult to evaluate." (PMID 34025668, 2021). "CXCL8 knockdown inhibits tumor growth in colorectal liver metastasis." (PMID 35011369, 2021). "CXCL8 is another interleukin that plays an essential role in tumor metastasis." (PMID 33390169, 2021). "Additionally, neovascularization, which provides a basis for fostering tumor growth and metastasis, is now recognized as a critical function of CXCL8 in the tumor microenvironment." (PMID 34640631, 2021). "Fusobacterium nucleatum may change tumor proliferation, invasion, metastasis, and drug resistance by increasing the expression of CXCL8 and reducing the expression of CXCL10, thus affecting the prognosis of patients." (PMID 34439306, 2021). "The relationship between chosen risk factors (serum CXCL8 and its specific receptor —CXCR2 as well as classical tumor markers and CRP) and GC risk was examined using univariate analysis to assess the risk factors that subsequently were employed in the multivariate model." (PMID 34680333, 2021).
tumor (continued). "In addition, recent reports gradually showed that an increased level of CXCL8 mediates tumor metastasis, stemness, and ultimately induces chemoresistance in CRC." (PMID 34440739, 2021). "For instance, CXCR2 and CXCL8 are overexpressed in various human cancers, such as oesophageal cancer, pancreatic cancer and ovarian cancer, and this overexpression positively correlates with aggressive tumor behavior and poor prognosis." (PMID 34124076, 2021). "This is of importance as IL-6 and CXCL8 are considered important “oncogenic cytokines”, as they are able to cause EMT, stimulate angiogenesis and tumor growth, disrupt cell-cell communication, impede macrophage function and promote epithelial and endothelial cell migration and invasion." (PMID 35048046, 2021). "CXCL8 can induce normal ovarian fibroblasts to CAFs and stimulate xenograft tumor growth in mice." (PMID 35011369, 2021). "Next, we aimed to investigate whether suppression of p16 leads to decreased expression of IL6 and CXCL8 in tumor cells." (PMID 33550279, 2021). "Interestingly, a significant correlation was identified between CXCL8/9/10/11 expression and tumor infiltration by immune cell types." (PMID 34233297, 2021). "CXCL8 inhibition led to an impairment of tumor vascularization and tumor death." (PMID 35011369, 2021). "Tumor-associated macrophages (TAMs) also secrete IL-1β, which, together with the actions of TNF-α stimulate tumor angiogenesis by inducing the release of VEGF and CXCL8 by HNSCC cells." (PMID 35048046, 2021). "Our findings suggest that serum CXCL8 might be used as a potential biomarker in the diagnosis of GC patients, especially in combined assessments with classical tumor markers." (PMID 34680333, 2021). "In addition, tumor-infiltrating Treg cells showed distinct expression of chemokines and chemokine receptors, e.g., IL-8 (CXCL8), CX3CR1, CXCR7, and CCR10, some of which have been proposed as a prognostic marker and/or therapeutic target in cancer." (PMID 33976194, 2021). "Furthermore, CXCL8 is often secreted by tumor cells and acts as a pro-inflammatory chemokine in chronic HCV." (PMID 34680563, 2021). "Cytokines released by tumor cells such as G-CSF, CXCL8, and related chemokines have been shown to induce the production of NETs, which leads to immune escape of tumor cells and promote tumor growth and invasion, thus surrounding them and preventing them from being killed by immune cells." (PMID 34707085, 2021). "Additionally, the CXCL8/CXCR2 axis promotes angiogenesis, tumor development and is associated with poor prognosis." (PMID 33390169, 2021). "CXCL8 promotes the formation of tumor micro-environment (TME) and the enrichment of CSCs." (PMID 34217295, 2021). "We demonstrated statistically significant differences in CXCL-8 concentrations between tumor stages using the Kruskal–Wallis test (p = 0.029) and confirmed them with the post hoc Dwass–Steele–Critchlow–Fligner test in patients with stage III and IV of CRC (p = 0.021; data not shown)." (PMID 32192002, 2020). "Finally, the CXCL8-derived radiomics model combined with tumor stage performed high ability in predicting the prognosis of CRC patients in the prognostic testing cohort, with an area under the curve (AUC) of 0.774 [95% confidence interval (CI): 0.674–0.874]." (PMID 33178604, 2020). "The involvement of CXCL8 in tumor progression and angiogenesis were mediated by multifaceted signaling pathways including NF-κB, JNK, PI3K/Akt, p38 MAPK and ERK, in which ERK signal pathway is a crucial mediator of a variety of cancer cells fates including proliferation, migration and survival." (PMID 32766720, 2020). "In addition, CXCL8 is a pro-inflammatory cytokine produced by tumor cells, neutrophils, and endothelial cells." (PMID 33198757, 2020). "Accordingly, CXCL8 induced tumor cell invasiveness through a Brachyury-dependent process." (PMID 32582148, 2020).
tumor (continued). "However, little is known about the significance of serum CXCL-8 as a potential tumor marker in the diagnosis and progression of CRC." (PMID 32192002, 2020). "Interestingly, we observed that the digestion of NETs with DNase had a minor impact on tumor cell migration as well as in the CXCL8 and MMP9 gene expression." (PMID 32545405, 2020). "Therefore, we examined serum levels of CXCL-8 in relation to tumor stage, and clinicopathological parameters of CRC in order to evaluate its significance in CRC progression." (PMID 32192002, 2020). "It was demonstrated that CXCL8 expression by GBM may influence the trafficking of MDSCs into the tumor environment by acting on the CXCR2 receptor." (PMID 32456359, 2020). "Of interest was the fact that tumor cell-expressed CD90 was required for generating physical contacts between the tumor cells and macrophages, and these interactions have increased the expression of IL-6, CXCL8 and granulocyte-macrophage colony stimulation factor (GM-CSF) in the cancer cells." (PMID 33585241, 2020). "Both normal human thyrocytes and tumor thyroid cells can secrete CXCL8." (PMID 32626535, 2020). "CXCL8 is a key mediator that recruits Treg cells into the tumor microenvironment." (PMID 31927532, 2020). "Finally, mechanism studies demonstrated that overexpression of CXCL8 in HepG2 cells regulates tumor-specific protein expression including ERK1/2, BAX and survivin." (PMID 32766720, 2020). "The influence of CXCL8 on tumor angiogenesis is regulated by Bcl-xl protein." (PMID 32456359, 2020). "CXCL8 and its receptor are related to the development of various tumor types, especially CRC." (PMID 33537240, 2020). "Several publications have appeared in recent years documenting the increased expression of interleukin 8 (CXCL8, IL-8), interleukin 6 (IL-6), tumor necrosis factor (TNFα) in cancer cells, infiltrating neutrophils, endothelial cells and tumor-associated macrophages." (PMID 33266223, 2020). "IL8, MIF, and CXCL8 lead to neutrophils infiltration at the tumor site." (PMID 33374253, 2020). "CXCL8 may be secreted both by tumor cells and TAMs, what facilitates cancer cells’ survival and induces resistance to the chemotherapy." (PMID 32456359, 2020). "Under the influence of various stimuli in the tumour microenvironment, stromal cells produce CXCL8, which may affect the invasiveness and metastatic potential of cancer cells." (PMID 32201645, 2020). "Statistically significant differences in CXCL-8 concentrations between tumor stages were first established using the Kruskal–Wallis test (p = 0.029) and then confirmed by the post hoc Dwass–Steele–Critchlow–Fligner test in patients with stage III and IV of CRC (p = 0.021; data not shown)." (PMID 32192002, 2020). "Interestingly, it was revealed that CXCL8 secretion by GBM cells is induced by the necrotic cells existing within tumor tissue." (PMID 32456359, 2020). "Moreover, CXCL8 produced by tumor cells or by CXCL8-transgenic mice gave rise to elevated osteolysis in vivo, whereas antibodies to CXCL8 prevented bone damage and elevated the survival of mice." (PMID 32582148, 2020). "These failures may arise due to acquired resistance in the tumour, such as the induction of alternative pro-angiogenic pathways (e.g. overexpression of CXCL8 or FGF42–44)." (PMID 32214219, 2020). "However, the specific mechanism of CXCL8 affecting tumor prognosis needs further investigation in cells and animals." (PMID 33178604, 2020). "CXCL8 has been shown to promote tumor development in humans in a variety of ways." (PMID 33178604, 2020). "Among the upregulated molecules in the TAM-like macrophages, we observed that growth differentiation factor 15, neural cell adhesion molecule, and CXC chemokine ligand 8 (CXCL8, also known as IL-8) contribute to the tumor cell migration, progression, and poor prognosis of ESCC." (PMID 32457351, 2020). "Secondly, some clinical studies have shown that CXCL8 disorder is related to tumor prognosis." (PMID 33178604, 2020).